CX3CR1 (C-X3-C motif chemokine receptor 1)
Diseases named in the same sentence as CX3CR1 in open-access papers (continued):
Sharing a sentence is not in itself a finding about the gene and the disease.
hematoma (3 papers, 2014 to 2023). A hematoma is a collection of blood from a vascular structure into an extravascular space. "In in vivo and in vitro ICH models, fractalkine located in neuronal cells can interact with the unique fractalkine receptor CX3CR1 and promote hematoma absorption through the PPAR-γ/CD163/HO-1 signaling pathway." (PMID 36970539, 2023). "Arginase-1 expression was mainly detected in CX3CR1+ macrophages/microglia in the peri-hematoma region (arrows), suggesting that macrophages/microglia in the injured brain are polarized to the M2 phenotype." (PMID 27094968, 2016). "In a collagenase-induced ICH model, CX3CR1+ macrophages accumulated in the peri-hematoma region." (PMID 27094968, 2016). "This may suggest that the Ly6B.2+ cells, rather than CX3CR1+ monocytes, are involved in hematoma clearance." (PMID 25469644, 2014).
macular degeneration (3 papers, 2013 to 2022). Loss of vision in the central portion of the retina (macula), secondary to retinal degeneration. "Indeed, in keeping with this, CCR2 receptor inhibition in CX3CR1-deficient mice specifically has also been found to be protective in other pathological conditions such as macular degeneration." (PMID 29625610, 2018). "The CCL2/CX3CR1 deficient mouse may thus serve as a model for age-related atrophic degeneration of the RPE, including the dry type of macular degeneration, geographic atrophy." (PMID 23637822, 2013).
metastatic melanoma (3 papers, 2023 to 2024). A melanoma that has spread from its primary site to another anatomic site. "Although it remains unclear whether T-cell CX3CR1 is a predictor of response to combination chemo-immunotherapy, Yan and colleagues demonstrated that CX3CR1+CD8+ T cells withstand treatment with chemotherapy and are increased in response to chemo-immunotherapy in patients with metastatic melanoma." (PMID 37009132, 2023). "To this end, we evaluated surgically resected non-lymphoid primary or metastatic melanoma from seven patients using flow cytometry and found that approximately 11% (range 1.8%–19.8%) of CD8+ TILs expressed CX3CR1." (PMID 38881188, 2024).
neuropathy (3 papers, 2013 to 2023). A disorder affecting the nervous system that manifests with pain, tingling, numbness, and/or muscle weakness. "As a result, novel therapeutic interventions aimed at blocking CX3CR1 may prove to be beneficial in attenuating sensory abnormalities associated with neuropathies associated with CX3CL1 induction." (PMID 24175290, 2013).
parasitemia (3 papers, 2009 to 2025). "Group 1 patients, characterized by an elevated percentage of CD14hi CCR2+CX3CR1+ MO, had a low mean parasitemia." (PMID 19851453, 2009). "Our results suggest this is a causal association as circulating MO expressing CCR2, CX3CR1, CD56, mTNF-α and mIFN-γ are not only associated with lower parasitemias but also are associated with strong ADCI activity." (PMID 19851453, 2009). "Furthermore, we have shown that patients with high numbers of CD14hi CCR2+CX3CR1+ MO had lower parasitemias than patients with low numbers of CD14hi CCR2+CX3CR1+ MO." (PMID 19851453, 2009). "In the group of patients with the highest percentages and absolute numbers of CD14hiCCR2+CX3CR1+ MO and the highest mean levels of ADCI activity, blood parasitemias were lower (0.14±0.34%) than in the second group (1.30±3.34%; p = 0.0053)." (PMID 19851453, 2009). "The observed tissue-specific effects of CX3CR1 inhibition likely reflect the distinct immunological microenvironments and differential parasite loads in different tissues during acute T. cruzi infection, even without altering blood parasitemia." (PMID 40936920, 2025).
retinal disease (3 papers, 2016 to 2019). "In the retina, the loss of CX3CR1 signaling in retinal disease has been associated with alterations in pathological phenotypes in mouse models of retinal diseases such as diabetic retinopathy, glaucoma, uveitis, oxidative injury, and light‐induced injury." (PMID 27314452, 2016). "The Cx3cr1-Cx3cl1 axis, a neuron-to-microglia signaling chemokine axis, has been shown to influence microglial activation, migration and proliferation in several retinal disease models." (PMID 30909963, 2019). "As a further test of the role of microglia in prion-induced photoreceptor degeneration, we also studied prion-induced retinal disease in mice homozygous for expression of a GFP transgene in place of the Cx3cr1 open reading frame, resulting in knockout of Cx3cr1 expression (tgGFP-Cx3cr1KO)." (PMID 30909963, 2019). "Accordingly, it has been demonstrated that increasing FKN/CX3CR1 signaling via iv delivery of FKN, dampens microglial activation and photoreceptor degeneration in a model of retinal disease." (PMID 28119571, 2016).
rheumatic diseases (3 papers, 2015 to 2025). "Integrated meta‐analyses of gene expression profiles identified CX3CR1 as a marker for rheumatic diseases." (PMID 39835465, 2025). "We identified a total of eight differentially expressed genes (TNFSF10, CX3CR1, LY96, TLR5, TXN, TIA1, PRKCH, PRF1), each associated with at least 3 of the 4 studied rheumatic diseases." (PMID 26352601, 2015). "Emerging evidence claims that FKN could be expressed in numerous tissues, taking part in the CX3CR1‐positive cell accumulation at sites of inflammation and, as a result, be involved in multiple rheumatic diseases such as RA, SLE, and scleroderma." (PMID 39392260, 2024). "By jointly analyzing 6 published microarray gene expression datasets about RA, SLE, OA and AS, we identified eight genes (TNFSF10, CX3CR1, LY96, TLR5, TXN, TIA1, PRKCH, PRF1) presenting general importance to rheumatic diseases." (PMID 26352601, 2015).
Salmonella Infections (3 papers, 2010 to 2025). Infections with bacteria of the genus SALMONELLA. "In addition CX3CR1+ DCs initiate the host defence to intestinal pathogens, such as Salmonella, as shown by the enhanced susceptibility of CX3CR1-deficient animals to Salmonella infection." (PMID 21152123, 2010).
sarcoma (3 papers, 2023 to 2024). A usually aggressive malignant neoplasm of the soft tissue or bone. "Moreover, reduced numbers of CX3CR1+CD206+ myeloid cells were associated with a positive response to anti-PD-1 therapy in a T3 sarcoma mouse model." (PMID 37771579, 2023). "An immune suppressive myeloid population defined as CX3CR1+CD206+ may strongly influence the outcome of the response to anti-PD-1 therapy since tumor-CX3CR1+CD206+ myeloid cells were reduced after response to anti-PD-1 in a T3 sarcoma mouse model." (PMID 37771579, 2023). "T‐cells in the sarcoma microenvironment exhibited elevated levels of cytotoxicity (GZMB, GNLY and KLRD1), exhaustion (HAVCR2, CD38, CD160, CXCL13 and CX3CR1), and inflammation (IL33, PPARG, IL6R and SOCS3), suggesting an activated but exhausted phenotype." (PMID 39658531, 2024). "We previously demonstrated that anti-CTLA-4 and/or anti-PD-1 induces macrophage TME remodeling characterized by a reduction in M2-like macrophages co-expressing the fractalkine receptor (CX3CR1) and CD206 and an increase in M1-like iNOS+ macrophages in mouse MCA sarcoma models." (PMID 38187708, 2024). "In MCA sarcoma models, we found that ICT-driven induction of iNOS+ macrophages was dependent upon IFN-γ, whereas ICT-driven depletion of CX3CR1+CD206+ macrophages was partially independent of IFN-γ19." (PMID 38187708, 2024).
schistosomiasis (3 papers, 2012 to 2026). An infectious disease caused by parasitic trematodes of the genus Schistosoma that colonize human blood vessels and release eggs that can cause granulomatous reactions leading to acute (swimmer's itch or acute schistosomiasis syndrome) or chronic disease. "We thus next examined STAT6 and PPAR-γ signaling to address the mechanisms by which Cx3cr1 deficiency skews macrophages towards M2 polarization during acute schistosomiasis." (PMID 26035381, 2015). "Taken together, our data demonstrate that Cx3cr1 deficiency leads to a typical switch of the host immune defense from a conventional Th1 to a typical Th2 response during acute schistosomiasis." (PMID 26035381, 2015). "Loss of Cx3cr1 rendered macrophages preferentially towards M2 polarization, which then led to a characteristic switch of the host immune defense from a conventional Th1 to a typical Th2 response during acute schistosomiasis." (PMID 26035381, 2015). "Taken together, our data support the hypothesis that that inhibition of Cx3cr1 signaling could be an effective approach to limit pro-inflammatory responses and granuloma formation during acute schistosomiasis." (PMID 26035381, 2015). "Nevertheless, our present data provide evidence supporting the hypothesis that CX3CR1 could be a viable therapeutic target during schistosomiasis." (PMID 26035381, 2015). "Taken together, our data provide evidence suggesting that CX3CR1 could be a viable therapeutic target for treatment of acute schistosomiasis." (PMID 26035381, 2015). "Since other researches described the up-regulation of CX3CR1 during liver damage, our converse result suggested that the transcription of this receptor on HSCs was distinct from that on other CX3CR1+ cell subpopulation such as KCs and epithelial cells in damaged liver of schistosomiasis." (PMID 22905138, 2012).
serous ovarian carcinoma (3 papers, 2015 to 2024). "Our data analysis demonstrated that both OS and PFS for patients with serous ovarian carcinoma expressing high CX3CR1 is significantly shorter than that for patients with low CX3CR1." (PMID 29712888, 2018). "Both CX3CR1 and CX3CL1 are expressed by the serous ovarian carcinoma." (PMID 26633537, 2015). "In opposite, both CX3CR1 and CX3CL1 are expressed in high-grade serous ovarian carcinoma." (PMID 26633537, 2015).
Sjögren's syndrome (3 papers, 2020 to 2025). "A previous study showed that CTSS-mediated induction of CX3CL1 might contribute to the ocular surface and lacrimal glands inflammation in Sjögren's syndrome with a 4.5-fold increase in CX3CR1-expressing macrophages." (PMID 33553270, 2020).
adenoma (2 papers, 2018 to 2020). A neoplasm arising from the epithelium. "Finally, given the role of CX3CR1 in regulating intestinal inflammation, we compared the formation of small intestine adenomas in APC+/min-CX3CR1+/- and APC+/min-CX3CR1-/-." (PMID 30140377, 2018). "More specifically, genes with such a therapeutic potential in non-functioning adenomas included CACNA2D4, IDH1, AURKB, GRIA2, PTGS2 and CX3CR1." (PMID 33168897, 2020).
alcoholic steatohepatitis (2 papers, 2018 to 2022). "H2S inhibits the accumulation of CX3CR1+ cells and alleviates alcoholic steatohepatitis." (PMID 35754513, 2022).
anemia (2 papers, 2014 to 2023). A reduction in the number of red blood cells, the amount of hemoglobin, and/or the volume of packed red blood cells. "We also observed associations of decreased monocyte numbers and CX3CR1 expression with anemia." (PMID 25105870, 2014). "FKN triggers the secretion of the receptivity-related cytokines at anemia that may improve endometrium receptivity via the CX3CR1 and the regulation of the NFκB pathway." (PMID 37175630, 2023). "FKN induces the secretion of the receptivity-related cytokines at anemia, which may improve endometrium receptivity via the CX3CR1 and the regulation of the NFκB pathway and by regulating activin, follistatin, and BMP2, as well as PR, SOX-17, PTGER2, and TIMP2." (PMID 37175630, 2023). "Although our previous study revealed that SOX-17 expression is operated by CX3CR1-mediated PR activation, the action of FKN on SOX-17 protein expression is controversial in anemia, probably due to the altered level of progesterone in a serum-free medium." (PMID 37175630, 2023). "Our findings support the hypothesis that FKN ameliorates the effects of anemia on the receptivity-related genes and proteins in HEC-1A cells by increasing the secretion of the receptivity-related cytokines via the fractalkine receptor (CX3CR1)." (PMID 37175630, 2023).
aneurysm (2 papers, 2014 to 2019). Bulging or ballooning in an area of an artery secondary to arterial wall weakening. "We find significant increases in EPHA4 expression concomitant with IL6, CX3CR1, and MCP1 in unruptured and ruptured aneurysms compared to superficial." (PMID 31711546, 2019).
brain inflammation (2 papers, 2010 to 2023). "We next compared the responses of male and female Cx3cr1::CreERT2; Nr1d1fl/fl mice and Cre− controls to LPS-induced brain inflammation." (PMID 37626048, 2023). "Thus, CX3CR1-mediated regulation of IL-1β expression in microglia may play an important role in the resolution of brain inflammation and sickness behavior." (PMID 21167054, 2010).
chronic Hepatitis B (2 papers, 2015 to 2025). "The aims of this study were to examine the role of CX3CR1 gene variants in Tunisian chronic hepatitis B patients and to analyze the correlations between CX3CR1 polymorphisms and the demographic and clinical features of the patients." (PMID 40733585, 2025). "To investigate whether CX3CR1 may regulate chronic hepatitis B virus (CHB) disease, we aimed to study genetic variants associated with susceptibility to chronic hepatitis B infection." (PMID 40733585, 2025). "In total, 280 patients with chronic hepatitis B and 260 controls from different cities of Tunisia recruited in the Pasteur Institute of Tunisia between January 2017 and December 2022 were genotyped for the V249I and T280M CX3CR1 gene." (PMID 40733585, 2025).
Cirrhosis (2 papers, 2012 to 2021). A chronic disorder of the liver in which liver tissue becomes scarred and is partially replaced by regenerative nodules and fibrotic tissue resulting in loss of liver function. "Furthermore, by enabling CX3CR1+ macrophage accumulation in the damaged area, γ-sEVs ameliorated inflammation and fibrosis in the cirrhosis mouse model more effectively than sEVs." (PMID 33785758, 2021).
crescentic glomerulonephritis (2 papers, 2022 to 2024). A histopathologic term for a pattern of diseases characterized by extensive crescent formation in the glomeruli; patients present clinically with rapid deterioration of renal function, and possible progression to end-stage renal failure within weeks or months. "CX3CL1 mRNA expression has been observed in glomerular lesions of patients with vascular disease, and in a rat model of crescentic glomerulonephritis, inhibition of CX3CR1 attenuated glomerular leukocyte influx and reduced crescent formation." (PMID 38937701, 2024).
cystic kidney disease (2 papers, 2023 to 2025). A congenital or acquired kidney disorder characterized by the presence of renal cysts. "Our data indicate that loss of Cx3cr1 significantly reduced cystic kidney disease in our IR injury accelerated model." (PMID 37256130, 2023). "The accumulation of Ccr2+ KTRM in the renal cortex under the regulation of CX3C chemokine receptor 1 (CX3cr1) can promote the progression of cortical-based cystic kidney disease." (PMID 40230850, 2025). "We also identified Cx3cr1 as a gene that governs cortex specific accumulation of Ccr2+ KRM and show that loss of Ccr2+ KRM reduces the severity of cystic kidney disease in a mouse model where cysts are mainly localized to the kidney cortex." (PMID 37256130, 2023).
demyelinating disease (2 papers, 2019 to 2021). A broad group of disorders that affect the myelin sheaths that cover the neurons. "In CX3CR1−/− mice with demyelinating disease, the clearance of myelin debris by microglia was substantially inhibited, affecting the integrity of the axon and myelin sheaths and thus preventing remyelination." (PMID 34646136, 2021).
demyelination (2 papers, 2023 to 2025). "In a cuprizone demyelination model, loss of Cx3cr1 attenuated the appearance of CD11c+ microglia, indicating that CD11c induction depends on CX3CR1-mediated phagocytic activity." (PMID 41373648, 2025). "Our data demonstrate exogenous FKN engages parenchymal OPCs, which express Cx3cr1, for oligodendrocyte regeneration and remyelination in a cuprizone demyelination mouse model." (PMID 36608690, 2023).
diffuse large B-cell lymphoma (2 papers, 2017 to 2023). "Despite their critical roles in angiogenesis and host immunosuppression within the tumor microenvironment, the prognostic significance of myeloid-lineage cells expressing CD11b and CX3CR1 in diffuse large B-cell lymphoma (DLBCL) has not been well studied." (PMID 29190915, 2017).
dilated cardiomyopathy (2 papers, 2022 to 2023). Cardiomyopathy which is characterized by dilation and contractile dysfunction of the left and right ventricles. "The evidence base and existing literature suggest that upregulation of CX3CR1, migration of immune cells, together with cytomegalovirus (CMV) seropositivity is associated with worse outcomes in patients with dilated cardiomyopathy." (PMID 37830591, 2023). "The evidence base and existing literature suggest that upregulation of fractalkine/CX3CR1, together with CMV seropositivity and consequent migration of immune and inflammatory cells, is associated with worse outcomes in patients with inflammatory conditions including dilated cardiomyopathy." (PMID 37830591, 2023). "While CXCL9, CXCL10, and CXCL11 belong to the chemokine family, CX3CR1, ADORA3 and SAA1 have not been reported in dilated cardiomyopathy, and further research is needed." (PMID 35618744, 2022).
emphysema (2 papers, 2019). "CX3CR1 may play an important role in lung inflammation and is involved in emphysema pathogenesis related to cigarette smoke." (PMID 31382977, 2019). "CX3CR1 plays an important role in the development of chronic inflammatory lung diseases, such as COPD and emphysema, by contributing to structural destruction and remodeling." (PMID 31419078, 2019).
endometrial cancer (2 papers, 2024 to 2025). Primary or metastatic malignant neoplasm involving the endometrium (mucous membrane that lines the endometrial cavity). "TPX2 affects the malignant progression of endometrial cancer cells by coupling the CX3CR1/CXCL10 chemokine pathway to the PI3K/Akt signaling pathway." (PMID 40511304, 2025). "Sp1 regulates TPX2 expression, resulting in a cascade effect, in EC; it affects the malignant progression of endometrial cancer cells by coupling the CX3CR1/CXCL10 chemokine pathway to the PI3K/Akt signaling pathway." (PMID 38466034, 2024). "Sp1 negatively regulated TPX2 expression, affecting the malignant progression of endometrial cancer cells by coupling the CX3CR1/CXCL10 chemokine pathway to the PI3K/Akt signaling pathway." (PMID 38466034, 2024).
endothelial dysfunction (2 papers, 2009 to 2022). In vascular diseases, endothelial dysfunction is a systemic pathological state of the endothelium (the inner lining of blood vessels) and can be broadly defined as an imbalance between vasodilating and vasoconstricting substances produced by (or acting on) the endothelium. "M280/I249 variants of CX3CR1 are associated with an atheroprotective effect and reduced endothelial dysfunction." (PMID 19587779, 2009). "The aim of our study was to search for an association between V249I and T280M polymorphisms of CX3CR1, PE and endothelial dysfunction." (PMID 19587779, 2009).
ependymoma (2 papers, 2021 to 2023). A WHO grade II, slow growing tumor of children and young adults, usually located intraventricularly. "To explore the ontogenies of TAM subsets in spinal ependymomas, we employed RNA velocity analysis and identified two different origins of CD44+ TAMs, including both CD14+ monocytes and CX3CR1+ TAMs." (PMID 34824203, 2021).
gastric adeno carcinoma (2 papers, 2018 to 2022). "On the one hand, the CX3CL1/CX3CR1 signaling transduces antitumor effects going along with a better prognosis for the patient like in hepatocellular, gastric adeno carcinoma." (PMID 29867042, 2018).